MAPK8IP1 (mitogen-activated protein kinase 8 interacting protein 1)
Description:
The JNK-interacting protein (JIP) group of scaffold proteins selectively mediates JNK signaling by aggregating specific components of the MAPK cascade to form a functional JNK signaling module. Required for JNK activation in response to excitotoxic stress. Cytoplasmic MAPK8IP1 causes inhibition of JNK-regulated activity by retaining JNK in the cytoplasm and inhibiting JNK phosphorylation of c-Jun. May also participate in ApoER2-specific reelin signaling. Directly, or indirectly, regulates GLUT2 gene expression and beta-cell function. Appears to have a role in cell signaling in mature and developing nerve terminals. May function as a regulator of vesicle transport, through interactions with the JNK-signaling components and motor proteins. Functions as an anti-apoptotic protein and whose level seems to influence the beta-cell death or survival response. Acts as a scaffold protein that coordinates with SH3RF1 in organizing different components of the JNK pathway, including RAC1 or RAC2, MAP3K11/MLK3 or MAP3K7/TAK1, MAP2K7/MKK7, MAPK8/JNK1 and/or MAPK9/JNK2 into a functional multiprotein complex to ensure the effective activation of the JNK signaling pathway. Regulates the activation of MAPK8/JNK1 and differentiation of CD8(+) T-cells.
Synonyms: JIP-1; IB1; JIP1; PRKM8IP
Tractability: Small molecule: a structure with a bound ligand is known. Antibody: its Gene Ontology location is reachable by antibodies, with high confidence; the Human Protein Atlas places it where antibodies can reach. PROTAC: UniProt records ubiquitination sites on it; its protein half-life has been measured.
Gene: Protein-coding gene on chromosome 11 (45,885,618 to 45,906,470, forward strand). Ensembl gene ENSG00000121653.
Subcellular location: Cytoplasm; Cytoplasm, perinuclear region; Nucleus; Endoplasmic reticulum membrane; Mitochondrion membrane
Subcellular location (Human Protein Atlas): Plasma membrane
Gene Ontology:
Molecular function: kinesin binding; MAP-kinase scaffold activity; protein binding; JUN kinase binding; protein kinase inhibitor activity; mitogen-activated protein kinase kinase binding; mitogen-activated protein kinase kinase kinase binding; protein kinase binding
Biological process: JNK cascade; negative regulation of JUN kinase activity; positive regulation of JNK cascade; regulation of CD8-positive, alpha-beta T cell proliferation; regulation of JNK cascade; vesicle-mediated transport; negative regulation of apoptotic process; negative regulation of JNK cascade
Cellular component: cytoplasm; plasma membrane; axon; axonal growth cone; cell body; cytosol; dendrite; dendritic growth cone; dentate gyrus mossy fiber; endoplasmic reticulum membrane; membrane; mitochondrial membrane; neuron projection; nucleus; perinuclear region of cytoplasm; synapse
Genetic constraint (gnomAD): Loss-of-function variants: 16 observed, 63.31 expected, observed/expected ratio (o/e) 0.25, 90% interval 0.17 to 0.38. The upper end of that interval is the gene's LOEUF score, 0.38, which puts it in group 1 of 6, group 1 being the genes least tolerant of losing a copy. Missense variants: 774 observed, 905.82 expected, observed/expected ratio (o/e) 0.85, 90% interval 0.81 to 0.91. Synonymous variants: 398 observed, 390.09 expected, observed/expected ratio (o/e) 1.02, 90% interval 0.94 to 1.11.
Homologues: Orthologues: chimpanzee MAPK8IP1 (99% identical), macaque MAPK8IP1 (95% identical), dog MAPK8IP1 (95% identical), pig MAPK8IP1 (95% identical), mouse Mapk8ip1 (93% identical), guinea pig MAPK8IP1 (92% identical), rat Mapk8ip1 (90% identical), tropical clawed frog mapk8ip1 (64% identical), zebrafish mapk8ip1a (49% identical), zebrafish MAPK8IP1 (31% identical), Caenorhabditis elegans jip-1 (25% identical), Drosophila melanogaster Aplip1 (19% identical), and 8 more. Paralogues in human: MAPK8IP2 (42% identical), NOS1AP (9% identical), GULP1 (9% identical), NUMB (8% identical), NUMBL (8% identical), DAB2 (8% identical), FAM43A (6% identical), DAB1 (6% identical), FAM43B (6% identical), LDLRAP1 (4% identical), C1orf226 (1% identical).
Diseases named in the same sentence as MAPK8IP1 in open-access papers:
MAPK8IP1 is named in the same sentence as 37 diseases in open-access papers, as found by Europe PMC text mining. Sharing a sentence is not in itself a finding about the gene and the disease. The quoted sentences say what the papers report.
Obesity (6 papers, 2018 to 2024). Accumulation of substantial excess body fat. "Eighteen of those genes have reported associations with T2D and obesity in humans; of these genes there was most marked evidence for CLEC10A, MAPK8IP1, NEGR1, NQ01 and INHBE genes." (PMID 34391409, 2021). "Moreover, Mapk8ip1-defective mice fed with high-fat diet (HFD) were protected against insulin resistance and obesity compared to HFD-fed WT mice." (PMID 36837926, 2023).
diabetes (4 papers, 2015 to 2023). "This is an interesting finding, as previous reports documented that a large fraction of diabetic patients with mutant Mapk8ip1 allele were also carriers of a Pdx1 mutation, which was previously associated with a late-onset form of diabetes." (PMID 36837926, 2023). "Mitogen-activated protein kinase 8 interacting protein-1 (MAPK8IP1) gene has been recognized as a susceptibility gene for diabetes." (PMID 36837926, 2023). "To date, the function of MAPK8IP1 in pancreatic β-cell physiology and the pathogenesis of diabetes remains elusive." (PMID 36837926, 2023). "Mitogen activated protein kinase 8 interacting protein 1 also called islet brain 1 (IB1) is a candidate gene for diabetes that is required for beta cell survival and glucose-induced insulin secretion (GSIS)." (PMID 26665154, 2016). "Although MAPK8IP1 has been identified as a potential candidate gene for T2D, other studies have demonstrated that the loss of MAPK8IP1 function did not contribute to the development of diabetes." (PMID 36902422, 2023). "Exploration of the effect of diabetes/hyperglycemia status on the mRNA expression of MAPK8IP1 showed a significant reduction in the case of diabetic/hyperglycemic islets (HbA1C ≥ 6%; n = 21) compared to nondiabetic/normoglycemic islets (HbA1c < 6%; n = 50) (p = 0.04)." (PMID 36837926, 2023). "The role of MAPK8IP1 in the development of diabetes is disputable." (PMID 36837926, 2023). "The function of MAPK8IP1 in the evolution of diabetes is controversial." (PMID 36837926, 2023). "To date, the function of MAPK8IP1 in pancreatic β-cell physiology and the pathogenesis of diabetes has not been entirely investigated." (PMID 36837926, 2023). "This was accomplished by analysis of the RNA-sequencing data and monitoring the expression of MAPK8IP1 in human pancreatic islets with/without diabetes." (PMID 36837926, 2023).
glioma (4 papers, 2017 to 2021). A benign or malignant brain and spinal cord tumor that arises from glial cells (astrocytes, oligodendrocytes, ependymal cells). "We observed that gliomas with high risk scores expressed SH3GLB1, whereas those with low risk scores expressed MAPK8IP1." (PMID 28977840, 2017). "In our study, upregulation of the autophagy-related gene MAPK8IP1 suppressed proliferation, migration and invasion of glioma cells." (PMID 28977840, 2017). "Analysis using a Cox proportional hazard regression model showed that MAPK8IP1 and SH3GLB1, two autophagy-related genes, were associated with the prognostic signature for glioma." (PMID 28977840, 2017). "Our data suggested that both SH3GLB1 and MAPK8IP1 interacted with other autophagy-related components and were involved in the pathogenesis of glioma." (PMID 28977840, 2017). "To investigate the effect of MAPK8IP1 on the biological behavior of glioma cells, we transfected T98G cells with the MAPK8IP1 plasmid and demonstrated that MAPK8IP1 was overexpressed by qRT-PCR and western blot analysis." (PMID 28977840, 2017). "Treatment of T98G cells that overexpressed MAPK8IP1 with 100μM Temozolomide suppressed proliferation and invasion suggesting that MAPK8IP1 overexpression increased the sensitivity of gliomas to Temozolomide treatment." (PMID 28977840, 2017). "This suggested that the two autophagy related genes, SH3GLB1 and MAPK8IP1 had opposite effects on glioma progression." (PMID 28977840, 2017). "Also, transcription factors interacting with MAPK8IP1 and SH3GLB1 were involved in multiple pathways like TGF, Hedgehog and WNT/Wingless signaling, which were associated with glioma." (PMID 28977840, 2017). "MAPK8IP1 was down-regulated in glioma samples from the CGGA Batch 1 dataset." (PMID 28977840, 2017). "Therefore, we analyzed the expression of MAPK8IP1 in five glioma cell lines by qRT-PCR." (PMID 28977840, 2017). "Glioma patients from the CGGA batches 1 and 2, GSE4412 and TCGA datasets could be divided into high- and low-risk groups with different survival times based on levels of MAPK8IP1 and SH3GLB1 expression." (PMID 28977840, 2017). "Compared to oligodendrocytes, three glioma cell lines (SNB19, U251, T98G) had low MAPK8IP1 mRNA levels, whereas two glioma cell lines (LN229, U87) showed higher MAPK8IP1 transcripts." (PMID 28977840, 2017). "We also identified two genes, MAPK8IP1 and SH3GLB1, which precisely predicted clinical outcomes of glioma patients." (PMID 28977840, 2017). "We identified two genes, MAPK8IP1 and SH3GLB1 that accurately predicted the clinical outcome of glioma patients." (PMID 28977840, 2017). "This suggested that MAPK8IP1 played a tumor suppressor role, whereas SH3GLB1 was a oncogene in glioma." (PMID 28977840, 2017). "MAPK8IP1 overexpression and SH3GLB1 knockdown inhibited glioma cell proliferation, migration and invasion, and improved Temozolomide sensitivity." (PMID 28977840, 2017). "We demonstrated that MAPK8IP1 overexpression and SH3GLB1 knockdown inhibited the proliferation, migration and invasion of glioma cells and increased sensitivity to Temozolomide." (PMID 28977840, 2017). "We demonstrated that MAPK8IP1 overexpression and SH3GLB1 downregulation increased the sensitivity of glioma cells to Temozolomide treatment." (PMID 28977840, 2017). "We also showed that MAPK8IP1 overexpression and SH3GLB1 knockdown inhibited proliferation, migration and invasion of glioma cells in addition to improving sensitivity to TMZ treatment." (PMID 28977840, 2017). "Furthermore, we investigated the role of MAPK8IP1 and SH3GLB1 on glioma cell proliferation, migration, invasion and their effect on Temozolomide treatment." (PMID 28977840, 2017).
gastric cancer (3 papers, 2020 to 2024). A primary or metastatic malignant neoplasm involving the stomach. "It has been reported that miR-10a-5p directly targets MAPK8IP1 as a major mechanism for gastric cancer metastasis." (PMID 34790823, 2021). "However, in gastric cancer, its expression is decreased, and overexpression of MAPK8IP1 can inhibit the metastatic ability of gastric cancer cells." (PMID 38321105, 2024). "In gastric cancer, miR-10a promotes cell migration and invasion by downregulating MAPK8IP1." (PMID 32260415, 2020).
Hyperglycemia (2 papers, 2019 to 2023). An increased concentration of glucose in the blood. "In mice, loss of Gpd2 is associated with decreased insulin secretion; loss of Neurod1 is associated with hyperglycemia; loss of Mapk8ip1 is associated with abnormal gluconeogenesis and increased insulin sensitivity." (PMID 31776723, 2019). "This raises the question of whether the reduction of MAPK8IP1 is involved in the pathogenies of T2D or just a consequence of hyperglycemia exposure (glucotoxicity)." (PMID 36837926, 2023).
insulinoma (1 paper, 2023). "Moreover, a series of functional experiments were executed in a rat insulinoma cell line (INS-1 832/13) to investigate the role of the Mapk8ip1 gene in β-cell function." (PMID 36837926, 2023).
keratoconus (1 paper, 2024). A degenerative, structural disorder of the eye, characterized by a cone-shaped protrusion of the cornea. "The expression of CCR2, CDKN1A, HSPA5, MAPK8IP1, PPP1R15A, and VEGFA in individuals with keratoconus was significantly different from that in control subjects." (PMID 38830963, 2024).
malignant glioma (1 paper, 2017). A grade III or grade IV glioma arising from the central nervous system. "Since the malignant glioma cell lines show highly invasive growth characteristics, both in vitro and in vivo, we performed wound-healing and transwell invasion assays to test the effects of MAPK8IP1 overexpression." (PMID 28977840, 2017).
nephrogenic diabetes insipidus type 1 (1 paper, 2025). "Variants were additionally found in genes linked to nephrogenic diabetes insipidus type 1 (AVPR2), the SLC2A2 gene encoding the GLUT2 protein, which plays a key role in glucose metabolism, and the MAPK8IP1 gene encoding a regulator of pancreatic beta-cell function." (PMID 40149731, 2025).
ovarian carcinoma (1 paper, 2020). A malignant neoplasm originating from the surface ovarian epithelium. "Overall, these observations suggest that ILK regulates the JNK/c-JUN pathway in cisplatin-resistant ovarian cancer via modulation of DUSP8, MARVELD3, PDCD4, MAPK8IP1, MAPK8IP2, and HIPK3." (PMID 32260415, 2020).
tumor (9 papers, 2007 to 2024). "Some genes encode proteins with functions related to signal transduction (PIK3R3, MAPK8IP1, and GATA2), and one gene encodes a protein that regulates tumor invasion and metastasis (TIMP2)." (PMID 17498291, 2007). "Lastly, expression of C-jun amino-terminal kinase interacting protein 1 (MAPK8ip1), a negative regulator of MAPK8 (c-jun amino-terminal kinase), was upregulated 6.9-fold in DC-tumor hybrid cells." (PMID 26605345, 2015).
MAPK8IP1 also shares sentences with these, for which no sentence is quoted: Alzheimer disease (3 papers); Insulin resistance (3); prostate carcinoma (3); type 2 diabetes (3); cervical carcinoma (2); infection (2); neuroblastoma (2); alcohol dependence (1); asthma (1); breast carcinoma (1); Cerebral ischemia (1); cervical (1); deafness (1); dysthymia (1); Fanconi anemia (1); glomerulosclerosis (1); malaria (1); neurodegenerative disease (1); neurological diseases (1); non-alcoholic steatohepatitis (1); osteosarcoma (1); prostate adenocarcinoma (1); prostate tumor (1); retinal degeneration (1); viral infection (1); vitiligo (1).